RADIL (Rap associating with DIL domain)
Description:
Downstream effector of Rap required for cell adhesion and migration of neural crest precursors during development.
Synonyms: KIAA1849; FLJ10324; RASIP2
Tractability: No criterion of Open Targets' tractability assessment is met for any kind of drug.
Gene: Protein-coding gene on chromosome 7 (4,797,055 to 4,883,716, reverse strand). Ensembl gene ENSG00000157927.
Subcellular location (Human Protein Atlas): Nuclear membrane; Nucleoplasm
Gene Ontology:
Molecular function: protein binding; GTPase binding
Biological process: substrate adhesion-dependent cell spreading; neural crest cell migration; signal transduction
Cellular component: microtubule; protein-containing complex
Genetic constraint (gnomAD): Loss-of-function variants: 100 observed, 79.06 expected, observed/expected ratio (o/e) 1.26, 90% interval 1.08 to 1.49. The synonymous counts are far from expectation, so gnomAD's model fits this gene poorly and the ratio says little. Missense variants: 1,764 observed, 1,343.1 expected, observed/expected ratio (o/e) 1.31, 90% interval 1.26 to 1.37. Synonymous variants: 801 observed, 613.04 expected, observed/expected ratio (o/e) 1.31, 90% interval 1.23 to 1.38.
Homologues: Orthologues: chimpanzee RADIL (98% identical), macaque RADIL (95% identical), dog RADIL (81% identical), pig RADIL (81% identical), guinea pig RADIL (81% identical), rat Radil (81% identical), mouse Radil (81% identical), rabbit RADIL (79% identical), zebrafish radil (50% identical). Paralogues in human: RASIP1 (27% identical).
Diseases named in the same sentence as RADIL in open-access papers:
RADIL is named in the same sentence as 13 diseases in open-access papers, as found by Europe PMC text mining. Sharing a sentence is not in itself a finding about the gene and the disease. The quoted sentences say what the papers report.
breast carcinoma (1 paper, 2019). "Rap1a–RADIL signaling performs a critical role in the progression of breast cancer." (PMID 31448237, 2019). "Moreover, RAP1A-RADIL inside-out signaling which is essential for breast cancer cell migration and invasion, can be inhibited by KLF14 through binding to C-terminal PDZ domain of RADIL and restricting RADIL from interacting with activated RAP1A spatially." (PMID 31448237, 2019).
kidney cancer (1 paper, 2019). Primary or metastatic malignant neoplasm involving the kidney. "In the current study, though we found RADIL had a better AUC in all stages of kidney, liver, stomach, and pancreatic cancer, Cox regression analysis found that RADIL is a significant risk factor for the development of kidney cancer." (PMID 31448237, 2019). "We have identified RADIL as an accurate diagnosis and prognosis biomarker for kidney cancer occurrence and development at peripheral blood level in the current cohort." (PMID 31448237, 2019). "Among those factors, RADIL could promote kidney cancer development (HR > 1, P < 0.05) while CD8+ T cells could inhibit kidney cancer development (HR < 1, P < 0.05)." (PMID 31448237, 2019). "RADIL may be a new immunotherapy target for kidney cancer post kidney transplantation." (PMID 31448237, 2019). "Multivariable Cox regression analysis found that RADIL together with other factors (including age, stage III, stage IV and CD8+ T cells) play a key role in kidney cancer development." (PMID 31448237, 2019). "Furthermore, RADIL had a significant effect on accelerating the development of kidney cancer and a negative relationship with tumor-infiltrating CD8+ T cells." (PMID 31448237, 2019). "Cox regression analysis found that RADIL still affected kidney cancer development along with age (P < 0.001), stage III (P = 0.001), stage IV (P < 0.001), and tumor-infiltrating CD8+ T cells (P < 0.001) which were completely negative in the kidney cancer development." (PMID 31448237, 2019).
liver cancer (1 paper, 2019). An epithelial or non-epithelial malignant neoplasm that arises from the liver. "Tumor tissues had higher expression of RADIL in renal cancer (P = 0.027), liver cancer (P = 0.04) and stomach cancer (P = 0.0086) compared to the negative control groups." (PMID 31448237, 2019). "This division indicated that renal cancer, liver cancer, and stomach cancer patients in the RADIL high-expression group had poor outcomes, while patients in the RADIL low-expression group had a better OS (P < 0.001)." (PMID 31448237, 2019).
Obesity (1 paper, 2021). Accumulation of substantial excess body fat. "Evidence is limited on the direct connection between RADIL and BMI or obesity, but an earlier study demonstrated that gene RADIL was significantly associated with birthweight and birth weight has been shown to be linked to obesity." (PMID 33766110, 2021). "The two genes (P2RX4 and RADIL), identified in the IoW and further confirmed in the ALSPAC, had some limited evidence of connections with BMI or obesity." (PMID 33766110, 2021).
pancreatic cancer (1 paper, 2019). "We also found that RADIL had a similar trend to the entire cohort in renal, liver, stomach, and pancreatic cancer in the early stages (I and II)." (PMID 31448237, 2019). "Kaplan-Meier analysis indicated that RADIL was expressed significantly higher in the early stages (I and II) of kidney, liver, stomach, and pancreatic cancer, suggesting the potential use of RADIL in early diagnosis." (PMID 31448237, 2019). "We also found that while renal, liver, and stomach cancer patients had high expression of RADIL, pancreatic cancer patients had lower expression of RADIL." (PMID 31448237, 2019). "In contrast, the patients with pancreatic cancer in the RADIL high-expression group possessed a better OS (P < 0.001), suggesting that RADIL may play different roles in different kinds of tumors." (PMID 31448237, 2019). "Meanwhile, in pancreatic cancer, tumor tissues had a lower RADIL expression (P = 0.0062)." (PMID 31448237, 2019).
cancer (5 papers, 2019 to 2024). A tumor composed of atypical neoplastic, often pleomorphic cells that invade other tissues. "Genes potentially associated with cell migration and cancer metastasis included CNTN5, FN1, Integrin Subunit Beta 6 (ITGB6), EPHB1, Unc-5 Netrin Receptor D (UNC5D), SDK1, RADIL, LRRC7, PCDH11X, and ADAMTS9." (PMID 39770638, 2024). "Although knocking down RADIL did not reveal a mutant KRAS-specific toxicity, a significant decrease in cell viability upon RADIL knockdown suggested that RADIL is important for cancer cells in general." (PMID 35839996, 2022). "Additionally, RAP1A and RAP1B play different roles in cancer, promoting translocation of the Rap Associated with DIL Domain (RADIL) from the cytoplasm to the plasma membrane, increasing cell adhesion." (PMID 34359657, 2021). "Here, we used a slightly different approach, monitoring cell viability following depletion of RADIL and IPO7 in KRAS mutant, KRAS WT, and normal human cancer cell lines." (PMID 35839996, 2022). "Research done by groups at National Cancer Institut has shown that RADIL can regulate neutrophil adhesion and chemotaxis by RADIL-mediated integrin and focal adhesion kinase (FAK) activation, which has been reported as a potentially important new target for cancer therapy." (PMID 31448237, 2019). "In this current study, through genome-wide RNA-Seq profile analysis of post-Tx malignant blood samples and post-Tx non-malignant control blood samples (CTRL-Tx), we found Rap GTPase Interactor (RADIL) and Aprataxin (APTX) to be the most meaningful markers for cancer diagnosis." (PMID 31448237, 2019). "RADIL and IPO7 depletion, relative to the luciferase control knockdown, significantly reduced cell viability of cell lines harboring the mutant or WT KRAS, suggesting that these genes are important, but disrupting them does not produce specific toxicity in KRAS mutant cancer cells." (PMID 35839996, 2022).
tumor (3 papers, 2019 to 2024). "Thus, RADIL might be playing different roles in the migration of tumour cells that express specific KRAS point mutations." (PMID 37627169, 2023). "Additionally, RADIL gene expression increased significantly in a murine immune-tolerance tumor cell line when compared with the murine immune-susceptible tumor cell line, suggesting RADIL may play a key role in tumor immune resistance." (PMID 31448237, 2019). "Immunohistochemistry results showed a similar outcome to that of survival analysis, suggesting RADIL's different roles in various tumor types." (PMID 31448237, 2019). "We are currently working on the RADIL-relevant mechanisms which may be closely related to tumor-infiltrating CD8+ T cells." (PMID 31448237, 2019). "RADIL expression was different among the different tumor stages (P < 0.05)." (PMID 31448237, 2019). "In addition, RADIL gene expression increased significantly in murine immune-tolerance tumor cell lines." (PMID 31448237, 2019). "RADIL gene expression was significantly upregulated when immune resistance occurred, which could prove that RADIL could accelerate the RCC development when tumor cells escape from the CD8+ immune surveillance." (PMID 31448237, 2019).
RADIL also shares sentences with these, for which no sentence is quoted: brain tumors (1 paper); glioma (1); intracranial aneurysms (1); lung adenocarcinoma (1); renal carcinoma (1); stomach cancer (1).